FST (follistatin)
Diseases named in the same sentence as FST in open-access papers (continued):
Sharing a sentence is not in itself a finding about the gene and the disease.
metabolic disorders (6 papers, 2021 to 2024). "Studies have shown that elevated follistatin levels are associated with improved glucose metabolism and increased insulin sensitivity, suggesting a potential therapeutic target for metabolic disorders." (PMID 38793069, 2024). "Thus, follistatin has been suggested to have therapeutic potential for the treatment of metabolic disorders and PCOS through the increase in BAT mass and activity." (PMID 36289764, 2022). "Collectively, given the promising role of follistatin in a broad range of biological processes, including energy metabolism, a more comprehensive investigation is necessary to clearly understand its physiological role and therapeutic potential in metabolic disease." (PMID 34944728, 2021). "Therefore, follistatin may contribute to metabolic disease progression." (PMID 34944728, 2021). "The inhibitory effect of follistatin on activin A and additional members of the transforming growth factor (TGF)-β superfamily, such as myostatin and bone morphogenetic proteins, was shown to protect from metabolic diseases in experimental models." (PMID 36289764, 2022).
inflammation (3 papers, 2014 to 2022). Aberrant reaction of the microcirculation characterized by movement of fluid and leukocytes from the blood into extravascular tissues. "Follistatin has anti-inflammatory properties and has been seen to be decreased in cigarette smoke-exposed human bronchial epithelial cells and administration of follistatin was found to attenuate cigarette smoke-induced airway inflammation in mice." (PMID 34429114, 2021).
kidney disease (3 papers, 2019 to 2024). "This discovery highlights the potential use of follistatin in the assessment of kidney health and the diagnosis of renal disorders." (PMID 38534369, 2024). "Sp1 is an essential transcriptional regulator for the antifibrotic protein follistatin and was identified as a profibrotic factor in kidney disease." (PMID 36457754, 2022). "Importantly, we established that Sp1, which has thus far been identified as a profibrotic factor in kidney disease, is a critical transcriptional regulator for the antifibrotic protein FST." (PMID 30995923, 2019).
neuromuscular disease (3 papers, 2017 to 2024). "In this sense, the role of serum follistatin as a biomarker for neuromuscular diseases is less clear compared to myostatin, with some studies reporting normal levels, while others indicate increased levels compared to controls." (PMID 38487549, 2024). "Our data show that in several neuromuscular diseases the myostatin pathway is shut down at mRNA level in muscle biopsies, leading to low levels of circulating and endogenous muscle myostatin and high-levels of follistatin." (PMID 29192144, 2017). "In the present study, we evaluated the ability of the follistatin-based fusion protein ACE-083 to produce localized muscle hypertrophy and increased strength in normal mice and murine models of neuromuscular disease." (PMID 31388039, 2019). "Serum concentrations of myostatin (MSTN or GDF8), follistatin (FSTN), GDF11 and ACTIVIN A were determined in patients affected by several neuromuscular diseases with various levels of muscle atrophy and in controls." (PMID 29192144, 2017). "Concerning the neuromuscular diseases, in slowly progressive pathologies such as BMD or FSHD, an important variability of both myostatin and follistatin circulating proteins is observed across samples, suggesting that at least some patients may be eligible for an anti-myostatin approach." (PMID 29192144, 2017).
infection (2 papers, 2015 to 2021). The state of being infected such as from the introduction of a foreign agent such as serum, vaccine, antigenic substance or organism. "Follistatin was significantly reduced, while VEGF-C secretions remained at sham-infection control levels." (PMID 33434186, 2021). "Despite the fact that activins and follistatin are involved in the regulation of many of the immune cells and cytokines that are involved in the immune response to HCV, currently there is lack of studies on the role(s) of these molecules during the course of infection with HCV." (PMID 25969625, 2015).
kidney (2 papers, 2019 to 2023). "In the present study, we examined the expression and localization of follistatin in normal and ischemic rat kidneys and measured urinary follistatin in rats with renal ischemia to assess whether urinary follistatin could serve as a biomarker for acute kidney injury." (PMID 36899937, 2023).
skeletal dysplasia (2 papers, 2019 to 2023). Any Mendelian diseases that affects growth and development of the skeleton. "Overproduction of follistatin, which interferes with endochondral ossification and is thought to cause skeletal dysplasia, only explains part of the proband's phenotype." (PMID 30693671, 2019).
cardiac diseases (1 paper, 2025). "Follistatin-dependent neutralisation of activin A specifically influences the vascular component of cardiac diseases." (PMID 41198895, 2025).
myopathies (1 paper, 2019). "In the present study, we evaluated the potential of ACE-083 – a locally acting, follistatin-based fusion protein – as a novel therapeutic agent for focal or asymmetric myopathies." (PMID 31388039, 2019).
FST also shares sentences with these, for which no sentence is quoted: cardiovascular disease (4 papers); adenocarcinoma (3); Hyperinsulinemia (3); Chronic Hepatitis C (2); depression (2); muscular atrophy (2); myocardial infarction (2); non-small cell lung carcinoma (2); osteoarthritis (2); peripheral artery disease (2); prostate tumour (2); reproductive diseases (2); alcoholic fatty liver disease (1); American trypanosomiasis (1); aortic stenosis (1); arteriosclerosis (1); atopic dermatitis (1); cervical intraepithelial neoplasia (1); Chagas disease (1); chondrosarcoma (1); chronic heart failure (1); chronic rhinosinusitis (1); coloboma (1); Crohn disease (1); diffuse large B-cell lymphoma (1); embryonal carcinoma (1); endocrine diseases (1); female subfertility (1); focal epilepsy (1); head and neck squamous cell carcinoma (1).
A further 20 diseases each share a sentence with FST in 1 paper.